CDK1 (cyclin dependent kinase 1)
Diseases named in the same sentence as CDK1 in open-access papers (continued):
Sharing a sentence is not in itself a finding about the gene and the disease.
sarcoma (9 papers, 2019 to 2025). A usually aggressive malignant neoplasm of the soft tissue or bone. "As an example, bright cells had an increased ration of ATAC-seq signal in the promoter of CDK1 compared to dim cells amongst all five the sarcoma lines tested." (PMID 39789291, 2025). "CDK1, KIF11, AURKB, MAD2L1, BUB1B and CCNB2 were highly expressed in sarcoma and were markedly related to worse OS." (PMID 34838000, 2021). "CDK1 inhibitors currently are not available for sarcomas, as well as CDK4/6 targeted inhibitors such as palvociclib and ribociclib which are approved for breast cancer by the US Food and Drug Administration (FDA) also have not been approved yet for sarcomas." (PMID 38434982, 2024). "Dinaciclib (a multi-CDK inhibitor) also only had a small phenotypic effect on SW684 cells, In fact, the computed CDK1 activity in SW684 cells was the lowest of all cell lines and SW684 cells were the least Dinaciclib-responsive of all 17 sarcoma lines (Fig. EV3E)." (PMID 38177929, 2024). "We found that increased expression of CDK1 and CCNB1 in RMS is related with negative prognosis in sarcoma sufferers." (PMID 31870357, 2019).
cholangiocarcinoma (8 papers, 2020 to 2025). A carcinoma that arises from the intrahepatic biliary tree (intrahepatic cholangiocarcinoma) or from the junction, or adjacent to the junction, of the right and left hepatic ducts (hilar cholangiocarcinoma). "In patients with cholangiocarcinoma, up-regulation of CDK1 or PSMC2 (which regulates CDK1) has been associated with lymph node metastasis and advanced clinical stage and tumor grade, respectively." (PMID 36266723, 2022). "Pharmacological inhibition of CDK1 decreased the phosphorylation level of CDK1, inhibited cell proliferation and invasion, and arrested the cell cycle at the G1 or G2/M phase in human cholangiocarcinoma cell lines." (PMID 34895070, 2021). "In addition, Molport-003-703-800, which is a compound that is derived from pharmacophores-based virtual screening, could directly bind to CDK1 and exhibited anti-tumor activity in cholangiocarcinoma cells." (PMID 36224755, 2022).
colon adenocarcinoma (8 papers, 2019 to 2023). "Therefore, the decreased ubiquitination level of CDK1 might explain the high protein level in colon adenocarcinoma, which is highly associated with tumor metastasis." (PMID 33014840, 2020). "Firstly, we identified the largest number of altered ubiquitinated peptides derived from CDK1 in metastatic colon adenocarcinoma tissues." (PMID 33014840, 2020). "Data extracted from TCGA database revealed that CDK1 expression was notably higher in colon adenocarcinoma samples compared to matched TCGA normal tissues and GTEx data." (PMID 33014840, 2020). "The result showed that protein CDK1 was significantly upregulated in metastatic colon adenocarcinoma tissue." (PMID 33014840, 2020). "Indeed, CDK1 mutations (mostly SNPs) were identified in 0.74% of cancer patients, with the highest frequency in Uterine Corpus Endometrial Carcinoma (UCEC), Colon adenocarcinoma (COAD) and Skin Cutaneous Melanoma (SKCM)." (PMID 37898722, 2023). "In the present study, we propose CDK1 as the pro-metastatic protein in colon adenocarcinoma." (PMID 33014840, 2020). "We speculate that the altered ubiquitination of CDK1 may be a pro-metastatic factor in colon adenocarcinoma." (PMID 33014840, 2020). "We used proliferation/invasion assays, western blot, RT-qPCR, immunofluorescence staining and quantitative methylation to study glucocorticoid-GR signaling, including the involvement of CDK1, in human colon adenocarcinoma cell lines HT29 and T84 (a representative metastatic cell line)." (PMID 31375708, 2019).
colorectal tumors (8 papers, 2014 to 2025). "CDK1 controls the cell cycle and aids in the development of colorectal tumors via an iron-regulated signalling axis." (PMID 36900162, 2023). "These clinical results are consistent with our findings that CDK1/4 are highly expressed in colorectal tumor tissues and correlated with pathological stage, while CDK5 overexpression is associated with shorter OS." (PMID 35814446, 2022). "This is in contrast to findings from colorectal tumor when it has been shown that high nuclear/cytoplasmic ratio of CDK1 expression is connected with poor prognosis in this type of cancer." (PMID 26912061, 2016). "In the data sets, DSCC1 and CDK1 were significantly up-regulated in colorectal tumors compared with normal colonic tissues." (PMID 24465681, 2014). "Having established that multiple independent CDK1 siRNA duplexes caused CDK1 silencing and KRAS selectivity, we assessed cell growth inhibition in a panel of 20 genetically diverse colorectal tumour cell line models transfected with multiple different CDK1 siRNAs." (PMID 26881434, 2016). "The mRNA expression profiles from the CCLE database indicated that the mRNA level of CDK1 in ESCC cell lines was higher than that in most other types of tumor cells, including prostate tumor, lung small‐cell cancer, stomach tumor, colorectal tumor, etc.." (PMID 34586751, 2021).
diabetes (8 papers, 2019 to 2025). "Now, our phosphoproteomic study profiling human circulating EVs confirms the activation of CDK1 and PKCδ in humans with prediabetes and diabetes and suggests clinical utility for phosphoproteomics of circulating EVs." (PMID 35628588, 2022). "Over time, chronic hyperinsulinemia culminates in the development of liver disease and a diabetes-like phenotype, as observed in aged Cdk1 cKO liver by the presence of insulin resistance and a NASH-like phenotype that is potentially on course to oncogenesis." (PMID 33345777, 2020). "For example, we speculate that the highly elevated upstream activities of CDK1 and PKCδ (represented by its catalytic subunit PRKCD) in the prediabetes stage may contribute to the development of diabetes." (PMID 35628588, 2022).
head and neck squamous cell carcinoma (7 papers, 2015 to 2024). A squamous cell carcinoma that arises from any of the following anatomic sites: lip and oral cavity, nasal cavity, paranasal sinuses, pharynx, larynx, and salivary glands. "In head and neck squamous cell carcinoma, MIR205HG inactivates miR-590-3p, leading to increased expression of cyclin B, cdk1, and YAP." (PMID 38612418, 2024). "Database analysis revealed that CDK1 is overexpressed in head and neck squamous cell carcinomas (HNSCCs), especially the metastatic HNSCCs, and is negatively correlated with overall survival." (PMID 35806389, 2022).
HIV-1 infection (7 papers, 2008 to 2025). The type species of lentivirus and the etiologic agent of acquired immunodeficiency syndrome (AIDS). "The results of our study showed that CDK1 rs139245206 was significantly associated with HIV-1 infection under codominant and recessive model." (PMID 37468905, 2023). "In this study, 42 tSNPs in ATR, Chk1, Cdc25C and CDK1 gene were genotyped to analyze the association with susceptibility to HIV-1 infection and AIDS progress among MSM population in the northern China." (PMID 37468905, 2023). "In this study, we aimed to genotype SNPs of ATR, Chk1, Cdc25C and CDK1 genes at G2/M checkpoint and analyze their associations with the susceptibility to HIV-1 infection and AIDS progression in a northern Chinese MSM population." (PMID 37468905, 2023). "Rs34660854 and rs37568165 in ATR gene, rs12576279 and rs540436 in Chk1 gene, rs3756766 in Cdc25C and rs139245206 in CDK1 gene were associated with susceptibility to HIV-1 infection." (PMID 37468905, 2023). "The aberrant activation of Cdk1 is thought to be involved in apoptosis associated with HIV-1 infection and neurodegenerative illness." (PMID 36560797, 2022). "To determine if 14-3-3 interactions were altered by Vpr or HIV-1 infection, we examined the association of 14-3-3 θ with Cdk1, CyclinB1, and Cdc25C by co-immunoprecipitation (IP)." (PMID 18445273, 2008). "Interestingly, one of the RNAs bound by FUBP3 implicated in HIV-1 infection processes is CDK1, which also shows significant downregulation upon FUBP3 depletion." (PMID 40248217, 2025). "Therefore, GMDR software was used to investigate the impact of interaction between ATR, Chk1, Cdc25C and CDK1 gene polymorphisms on HIV-1 infection susceptibility." (PMID 37468905, 2023). "Actual HIV-1 infection (RT+) had the same effect, although this result was variable and occasionally less Cdk1 and CyclinB1 were recruited to 14-3-3 θ compared to Vprv treatment (HIV lane)." (PMID 18445273, 2008). "Despite numerous attempts, we were unable to detect an increase in phosphorylated, inactive Cdk1 in Jurkat cells blocked in G2,M by either Vprv or HIV-1 infection." (PMID 18445273, 2008). "Although we did not observe increased Cdk1 phosphorylation by Vpr or HIV-1 infection, the association of Cdk1 and CyclinB1 with 14-3-3 was significantly altered during Vpr-induced G2,M arrest." (PMID 18445273, 2008). "Together, these findings suggest that normal 14-3-3 activity within the centrosome is disturbed in HIV-1 infection-induced G2,M arrest and may be responsible for impaired Cdk1 activation." (PMID 18445273, 2008). "Although nuclear levels did not change, Vprv, but not HIV-1 infection, significantly increased cytoplasmic expression specifically of CyclinB1 and Polo-like kinase 1 (Plk1), but not Cdc25C and Cdk1." (PMID 18445273, 2008).
nasopharyngeal carcinoma (7 papers, 2019 to 2025). A carcinoma arising from the nasopharyngeal epithelium. "For example, miR-96-5p could inhibit the viability and promote the chemoradiotherapy sensitivity of nasopharyngeal carcinoma by targeting CDK1." (PMID 33715625, 2021). "In nasopharyngeal carcinoma, AMP-activated protein kinase (AMPK), and cyclin-dependent kinase 1 (CDK1) axis activity determines the balance of DRP1 phosphorylation at Ser616 and Ser637, leading to chemoresistance." (PMID 33804169, 2021). "In nasopharyngeal carcinoma, the overexpression of Chromosome 2 open reading frame 40 (C2orf40) regulates the PI3K/AKT/mTOR pathway, significantly reducing the protein expression levels of key cell cycle regulators, including Cyclin-dependent kinase 1 (CDK1), Cyclin E1, and Cyclin B1." (PMID 40725100, 2025).
pancreatic adenocarcinoma (7 papers, 2015 to 2025). "Wijnen and colleagues also confirmed that CDK1 is a prognostic risk gene for pancreatic adenocarcinoma and suggested that the inhibition of CDK1 could be a new strategy for the treatment of pancreatic adenocarcinoma." (PMID 37370756, 2023). "We identified seven prognostic genes (MET, DYNLL2, CDK1, TNFSF10, PIP5K1C, MSLN, GKN1) and validated that their related proteins, such as EGFR and MMP2, have a significant impact on the prognosis of pancreatic adenocarcinoma." (PMID 37370756, 2023). "Compared with normal tissues, the expression levels of MET, DYNLL2, CDK1, TNFSF10, PIP5K1C, MSLN, and GKN1 were significantly increased in pancreatic adenocarcinoma cells (p < 0.05)." (PMID 37370756, 2023).
rhabdomyosarcoma (7 papers, 2015 to 2025). A rare aggressive malignant mesenchymal neoplasm arising from skeletal muscle. "There is growing evidence found that CDK1 can be used as a potential biomarker for a variety of diseases, such as Rhabdomyosarcoma, endometrioid endometrial cancer." (PMID 35749386, 2022). "Although no previous studies have analyzed CDK1 overexpression in leiomyosarcomas versus leiomyomas through immunohistochemistry, CDK1 has been proposed as a potential diagnostic biomarker for rhabdomyosarcoma." (PMID 41162745, 2025). "Both mRNA and protein levels of cdk1 and CCNB1 were elevated in all NB cell lines and the human rhabdomyosarcoma cell line, RH-41, when compared to a human fibroblast cell line (NHDF)." (PMID 26029996, 2015). "NB cell lines derived from high-stage, aggressive tumors as well as the rhabdomyosarcoma cell line RH-41 all presented with high cdk1/CCNB1 expression independent of the MYCN amplification status." (PMID 26029996, 2015).
chronic lymphocytic leukemia (6 papers, 2008 to 2025). "miR-650 on chromosome 22 is located in the Ig λ light chain locus (IgL) and increased expression in B cell chronic lymphocytic leukemia (B-CLL) predicts a more favorable disease course and targets CDK1, ING4 and EBF3." (PMID 35202088, 2022). "Similarly, dinaciclib is a highly potent CDK inhibitor with selectivity for CDK1, CDK2, CDK5, and CDK9 in phase III clinical trials for the treatment of refractory chronic lymphocytic leukemia." (PMID 32412527, 2020). "Similarly, the CDK1 and CDK2 (CDK1/2) inhibitor dinaciclib entered a phase 3 trial in chronic lymphocytic leukemia." (PMID 25557169, 2015).
Cirrhosis (6 papers, 2012 to 2025). A chronic disorder of the liver in which liver tissue becomes scarred and is partially replaced by regenerative nodules and fibrotic tissue resulting in loss of liver function. "Similarly, when β was calculated when tumor size, BCLC stage and cirrhosis as adjusted factors, risk score = expression of CDK1 × 0.792 + expression of CDK4 × 0.024 in GSE14520 cohort." (PMID 35193513, 2022). "And some datasets lack detailed clinicopathological parameters (e.g., treatment history, cirrhosis background, and viral hepatitis infection status), which limits the precise resolution of the CDK1 mechanism of action." (PMID 40332418, 2025). "They found that RRM2, cyclin-dependent kinase 1 (CDK1), PDZ-binding kinase (PBK), abnormal spindle homolog, and microcephaly-associated Drosophila (ASPM) were key genes for HCC transformation from cirrhosis." (PMID 36768940, 2023). "Overall, critical genes encoding for positive cell cycle progression factors (CCND1, CDK1, CDK2, E2F3, EIF4E, and MDM2) were found significantly up-regulated in HCV-cirrhosis with HCC." (PMID 22792259, 2012).
esophageal squamous cell carcinoma (6 papers, 2021 to 2025). Esophageal squamous cell carcinoma (ESCC) is a type of esophageal carcinoma (EC) that can affect any part of the esophagus, but is usually located in the upper or middle third. "The results of PrognoScan analysis suggested that patients with CDK1-positive esophageal squamous cell carcinoma had better OS and RFS." (PMID 36090896, 2022). "Pleiotropy for statins is seen where the CDC28 human orthologue CDK1 is downregulated by atorvastatin with anticancer activity in esophageal squamous cell carcinoma (ESCC) cells." (PMID 36946734, 2023). "However, it remains unclear whether CDK1 plays a role in esophageal squamous cell carcinoma (ESCC)." (PMID 34586751, 2021).
hepatitis B (6 papers, 2020 to 2025). "The data of normal group-hepatitis B, hepatitis B-hepatitis B-related hepatocellular carcinoma, and hepatitis C-related cirrhosis-hepatitis C-related hepatocellular carcinoma all had two common targets CDK1 and TOP2A with YZHG putative targets." (PMID 35342754, 2022). "The normal group-hepatitis B, hepatitis B-hepatitis B-related hepatocellular carcinoma, and hepatitis C-related cirrhosis-hepatitis C-related hepatocellular carcinoma data have 2 common targets CDK1 and TOP2A with the predicted targets of YZHG." (PMID 35342754, 2022). "Among them, PTTG1, MAD2L1, CDK1, and NEK2 may be the key prognostic genes of the hepatitis B inflammation and cancer transformation." (PMID 34539726, 2021).
Infertility (6 papers, 2014 to 2024). "Deficiency of cdk1 in mouse ovulated oocytes prevents the cells from resuming the meiotic cycle and resulting in infertility." (PMID 38952806, 2024). "Previous research has demonstrated that CDK1 knockout mice experience infertility due to oocyte arrest at the GV stage." (PMID 37635245, 2023). "Accordingly, cdk-1 (RNAi) suppresses wee-1.3 (RNAi) infertility and therefore serves as a positive control in these studies." (PMID 36060813, 2022). "For example, suppressors that alter the trafficking or localization of CDK-1 could result in suppression of the WEE-1.3 depletion infertility." (PMID 25298536, 2014). "Co-depletion of CDK-1 and WEE-1.3 has been shown to suppress the infertility of WEE-1.3 depletion alone." (PMID 25298536, 2014). "This phenotype could be suppressed by the co-depletion of CDK-1 and WEE-1.3, resulting in broods of more than 100 one-cell arrested embryos, whereas co-depletion of an unrelated dsRNA (zyg-1) did not suppress the infertility of WEE-1.3 depletion." (PMID 25298536, 2014).
medulloblastoma (6 papers, 2014 to 2021). A malignant, invasive embryonal neoplasm arising from the cerebellum. "Overall, these results offer a mechanistic implication of the transcriptional CDK9 and to a lesser extent of the cell cycle related CDK1 in the phenotypic effects observed after in vitro treatments with dinaciclib on medulloblastoma cells." (PMID 33686114, 2021). "There were 57 up-regulated genes common to the tumors induced by rb1 somatic inactivation (zebrafish tumors) and human medulloblastomas and PNETs most of which were involved in cell cycle progression and mitosis (such as cdk1, aurka, plk1, etc.)." (PMID 28903419, 2017). "Given that Paullones, including alsterpaullone, have been identified as CDK1/CDK2/CDK5 and GSK3B inhibitors, we examined the gene expression profiles of the CDK genes in the Group 3 medulloblastoma cell lines." (PMID 26061748, 2015).
Obesity (6 papers, 2019 to 2025). Accumulation of substantial excess body fat. "However, persistent activation of CDK1 during obesity causes both beneficial and pathological consequences for the pancreatic beta cell in mice, including reduction in their insulin secretory capacity that is recovered by pharmacologic inhibition with RO-3306." (PMID 35628588, 2022). "This pathway is shown to be hyperactive in obese (ob/ob) mice wherein complex-I is identified as a critical modulator of obesity-induced metabolic remodeling in ß-cells which in turn is regulated by cyclin-dependent kinase-1 (CDK-1)." (PMID 33935708, 2021). "First, we observed higher Cyclin B2 and CDK1 expression in the cortex and hippocampus of obese mice than wild-type mice, indicating that G2/M checkpoint proteins increase under the condition of obesity-induced neurodegeneration." (PMID 34561612, 2021). "Therefore, we assume that abnormal expression of Cyclin/CDKs results in the low frequency of polyploidy in the brain with obesity because circTshz2-2 suppression reduced the expression of Cyclin B2 and CDK1 in the brain cortex and hippocampus of obese mice." (PMID 34561612, 2021). "Moreover, they found that CDK1 and PKCδ may play a critical role in the obesity-to-T2D progression, with elevated levels of these kinases contributing to reduced insulin secretion capacity and increased IR." (PMID 41441338, 2025).